SMARCAL1 (SNF2 related chromatin remodeling annealing helicase 1)
Diseases named in the same sentence as SMARCAL1 in open-access papers (continued):
Sharing a sentence is not in itself a finding about the gene and the disease.
atherosclerosis (1 paper, 2009). A disease characterized by the build-up of fatty material and calcium deposition in the arterial wall resulting in partial or complete occlusion of the arterial lumen. "Since mutations of SMARCAL1 alter transcription across chromatin domains containing many genes with altered transcription in atherosclerotic plaques, we hypothesize that the confluence of these multiple transcriptional changes predisposes to atherosclerosis." (PMID 19721813, 2009).
autonomous disorder (1 paper, 2012). "Consistent with a cell autonomous disorder, SMARCAL1 was expressed in arterial and lung tissue, and both the aorta and lung of SIOD patients had reduced expression of elastin and alterations in the expression of regulators of elastin gene expression." (PMID 22998683, 2012).
chondrosarcoma (1 paper, 2018). A malignant cartilaginous matrix-producing mesenchymal neoplasm arising from the bone and soft tissue. "Additionally, the SMARCAL1-mutated ALT-positive cell line we identified in our study, CAL78, is a chondrosarcoma cell line." (PMID 29802247, 2018).
chronic kidney disease (1 paper, 2025). Impairment of the renal function secondary to chronic kidney damage persisting for three or more months. "Overall, more than one-half of the children (57%, 12/21 patients) died during the observation period (patients No 1–6, 8, 9, 14, 18, 19, and one child without any pathogenic variants in SMARCAL1); three of them had not reached chronic kidney disease (CKD) stage 5 (patients No 1, 4, and 6)." (PMID 40004207, 2025).
Coffin-Siris syndrome (1 paper, 2022). Coffin-Siris syndrome (CSS) is a rare congenital multi-systemic genetic disorder characterized by aplasia or hypoplasia of the distal phalanx or nail of the fifth digit, developmental delay, intellectual disability, coarse facial features, and other variable clinical manifestations. "Mutations associated with SIOD and CSS4 impairs the co-localization: Mutations in SMARCAL1 cause Schmike Immuno‐osseous Dysplasia (SIOD) while mutations in BRG1 are associated with Coffin-Siris Syndrome (CSS4)." (PMID 35784471, 2022).
hepatoma (1 paper, 2023). "To reproduce this phenotype in a different cell type, we used a lentivirus-based CRISPR/Cas9 system to generate homozygous inactivation of the SMARCAL1 gene (SMARCAL1−/−) in human hepatoma Huh7 cells." (PMID 38129665, 2023).
Hypercholesterolemia (1 paper, 2023). An increased concentration of cholesterol in the blood.
intrauterine growth restriction (1 paper, 2020). "The younger brother, carrying the same homozygous variant in SMARCAL1, was born at 31 weeks of gestation, with a prenatal diagnosis of intrauterine growth restriction, multicystic left kidney, and a neoformation on the right kidney." (PMID 33203071, 2020).
lung carcinoma (1 paper, 2025). "Next, we assessed SMARCAL1 and CD276 expression in lung cancer cell lines PC9 and HCC827." (PMID 39994264, 2025).
Nephropathy (1 paper, 2017). A nonspecific term referring to disease or damage of the kidneys. "We analyzed the renal and extrarenal phenotypic spectrum and genotype-phenotype associations in 34 patients from 28 families, the largest SMARCAL1-associated nephropathy cohort to date." (PMID 28796785, 2017). "Median ESKD-free survival time was 8.7 (95% CI 8.0–9.4) years for SMARCAL1 vs. 13.0 (95%CI 11.8–14.1) years for NPHS2 nephropathy (p = 0.013)." (PMID 28796785, 2017).
Noonan-like syndrome (1 paper, 2025). "Mutations in SHOC2, which is involved in Noonan-like syndrome, were identified in two cases, and SMARCAL1 mutations associated with Schimke immuno-osseous dysplasia were confirmed in two additional cases." (PMID 40959740, 2025).
osteoporosis (1 paper, 2026). A condition of reduced bone mass, with decreased cortical thickness and a decrease in the number and size of the trabeculae of cancellous bone (but normal chemical composition), resulting in increased fracture incidence. "Adolescents with this condition often develop secondary osteoporosis and hip joint issues, indicating that Smarcal1 mutations disrupt bone metabolic homeostasis." (PMID 41550058, 2026).
promyelocytic leukemia (1 paper, 2025). "What is more, SMARCAL1 deficiency has been correlated with ALT activation, as cells lacking SMARCAL1 often exhibit ALT-associated promyelocytic leukemia bodies, which are hallmark features of the ALT pathway." (PMID 40723168, 2025).
prostate carcinoma (1 paper, 2021). A carcinoma that arises from epithelial cells of the prostate gland. "These prostate cancer cells, unlike HeLa cells, do not express BRG1 and SMARCAL1 either in the absence or in the presence of ADAADi." (PMID 33999958, 2021).
Proteinuria (1 paper, 2014). Increased levels of protein in the urine. "Our experience demonstrate that nephrotic proteinuria associated with a mild form of SIOD may respond to combined therapy with ACE- inhibitors and sartans, supporting the concept that several missense mutations in SMARCAL1 gene retain some residual function." (PMID 24589093, 2014).
pulmonary disease (1 paper, 2012). "Among SIOD patients with SMARCAL1 mutations, 22 of 51 (43.1%) patients had lung disease." (PMID 22998683, 2012). "To test these hypotheses and to determine the prevalence of vascular and pulmonary disease among SIOD patients, we reviewed the records of SIOD patients with identified SMARCAL1 mutations, delineated the arterial and pulmonary pathology and profiled gene expression in postmortem artery and lung." (PMID 22998683, 2012).
viral infection (1 paper, 2024). "However, recently, we reported that circumstances necessitating urgent DNA replication, such as acute responses to a mock viral infection (pI:pC injection), favored DNA fork repriming by PrimPol over fork reversal by Zranb3 or Smarcal1." (PMID 39044358, 2024). "However, neither Smarcal1 nor Zranb3 appear to be essential for the acute HSPC response to polyinosinic:polycytidylic acid (pI:pC) insult that mimics a viral infection." (PMID 39044358, 2024).
Wilms tumor (1 paper, 2022). An embryonal neoplasm characterized by the presence of epithelial, mesenchymal, and blastema components. "Thirty-seven percent of WT1-related SRNS showed genital abnormalities or a predisposition to Wilms tumor, 2 cases of SMARCAL1-related SRNS showed growth failure and poor cellular immunity." (PMID 35755072, 2022).
cancer (29 papers, 2013 to 2026). A tumor composed of atypical neoplastic, often pleomorphic cells that invade other tissues. "We also found significant associations between SMARCAL1 expression and DNA methylation in 13 cancers." (PMID 39994264, 2025). "Further investigations are warranted to validate the diagnostic utility of SMARCAL1 and delineate its involvement in the molecular pathogenesis of cancer." (PMID 39994264, 2025). "Our analysis indicated that higher SMARCAL1 expression posed a significant risk threat in most cancer types." (PMID 39994264, 2025). "In supporting this model, it has been recently discovered that SMARCAL1 loss-of-function mutations in cancers link to the ALT mechanism of telomere maintenance, resulting in ultrabright telomeric foci and the generation of C-circles." (PMID 30716077, 2019). "We then investigated the extent to which expression of wildtype (WT) SMARCAL1 or cancer-associated SMARCAL1 variants modulate ALT hallmarks in cell lines with native SMARCAL1 mutations." (PMID 29802247, 2018). "In conclusion, these studies identify novel biomarkers that can be used to objectively define TERTpWT-IDHWT GBM tumors and have discovered a novel role of somatic SMARCAL1 loss-of-function mutations in the ALT phenotype in human cancers." (PMID 29802247, 2018). "Our study reveals a novel role for somatic recurrent loss-of-function alterations in SMARCAL1 in cancers with the ALT telomere maintenance mechanism." (PMID 29802247, 2018). "To further explore the functional connection between somatic SMARCAL1 mutations and ALT, we identified two cancer cell lines harboring mutations in SMARCAL1, D06MG, and CAL-78." (PMID 29802247, 2018). "All SMARCAL1-mutant GBMs exhibited both ultrabright telomeric foci and C-circles, suggesting a novel link between somatic SMARCAL1 loss-of-function mutations in cancer and the ALT mechanism of telomere maintenance." (PMID 29802247, 2018). "Here, we show that cancers with somatic mutation of SMARCAL1 are ALT positive, and this represents, to our knowledge, the only other reported gene mutation associated with ALT other than ATRX and DAXX mutations." (PMID 29802247, 2018). "The identification of genetic mutations in ATRX, DAXX, H3.3, and more recently SMARCAL1 in ALT positive cancers has been instrumental in further defining the molecular basis of ALT." (PMID 30214690, 2018). "Cancer-associated mutations tested from our GBM cohort included SMARCAL1 Arg645Ser (R645S), Phe793del (del793), and Gly945fs*1 (945 fs)." (PMID 29802247, 2018). "In addition, we examined mutation patterns in pan-cancer TCGA (The Cancer Genome Atlas) data on cBioportal34 and found that SMARCAL1 mutations and homozygous deletions are present at low frequency in several other cancer types." (PMID 29802247, 2018). "Thus, inherited loss of function mutations in fork repair enzymes like WRN and SMARCAL1 cause diseases that include an increased predisposition to cancer." (PMID 23671665, 2013). "As for SMARCAL1, a possible ZRANB3 cancer-associated duality is intriguing, albeit at present it appears confined to this tissue." (PMID 41596226, 2026). "Results revealed Tipifarnib, Sorafenib, and PF-562271 as potential effective inhibitors of SMARCAL1, with most cancers showing sensitivity to them." (PMID 39994264, 2025). "SMARCAL1 expression and DNA methylation are closely correlated in a variety of cancer types, according to the reported data." (PMID 39994264, 2025). "By limiting DNA damage, SMARCAL1 helps cancer cells to avoid detection by this immune surveillance mechanism." (PMID 40629041, 2025). "This study aims to explore the expression characteristics of SMARCAL1 in pan-cancer, its prognostic value, and its relationship with immunotherapy." (PMID 39994264, 2025). "We conducted a comprehensive investigation into pan-cancer genetic alterations in SMARCAL1 utilizing data from the cBioPortal." (PMID 39994264, 2025).
cancer (continued). "The findings showed that SMARCAL1 was expressed differently in 27 different types of cancers, with 27 tumor types exhibiting higher expression." (PMID 39994264, 2025). "We investigated 22 different types of cancer tissues as well as normal tissues’ levels of promoter DNA methylation in SMARCAL1." (PMID 39994264, 2025). "Our findings revealed a significant decrease in promoter methylation levels across most cancer tissues, suggesting a potential oncogenic role of SMARCAL1 in pan-cancer." (PMID 39994264, 2025). "Analysis of the CGP dataset revealed correlations between SMARCAL1 mRNA expression levels and drug sensitivity across various cancers." (PMID 39994264, 2025). "Elevated SMARCAL1 expression across various cancers underscores its significance in tumor progression and immune evasion." (PMID 39994264, 2025). "We conducted a pan-cancer analysis of SMARCAL1 across 33 tumor types using the CCLE, TCGA, and GTEx databases." (PMID 39994264, 2025). "Targeted inhibition of SMARCAL1 induces cancer innate immune signaling while downregulating PD‐L1 levels, resulting in a double whammy for cancer and better cancer treatment outcomes." (PMID 39247620, 2024). "Loss of CSB leads to re-sensitization of SMARCAL1-depleted BRCA2-deficient cells to chemodrugs, underscoring a role of CSB in targeted cancer therapy." (PMID 38416570, 2024). "However, members of the SWI/SNF2 family of ATPases are frequently mutated in human cancer, behaving as tumor suppressors, and the function of SMARCAL1 in DNA transcription, replication, and repair could play a role in the development of malignancy if the gene is mutated." (PMID 33203071, 2020). "Transformed or cancer-derived SMARCAL1-depleted cells are characterized by elevated levels of DNA damage." (PMID 31515241, 2019). "We report the discovery of somatic SMARCAL1 loss-of-function mutations and their involvement in ALT-mediated telomere maintenance in cancer." (PMID 29802247, 2018). "In addition to offering a preliminary analysis of SMARCAL1’s relationship with immune cell infiltration, immune molecules, and markers of classical immune therapy, our findings shed important light on the potential of SMARCAL1 in cancer immunotherapy." (PMID 39994264, 2025). "Overall, our results show that SMARCAL1 may be important for cancer immunotherapy, and they also emphasize the need for more investigation to clarify its precise modes of action and therapeutic applications." (PMID 39994264, 2025). "Furthermore, SMARCAL1 expression correlates with immune infiltration, suggesting it as a potential therapeutic target in cancer immunotherapy." (PMID 39994264, 2025). "When SMARCAL1 function is lost, cancer cells experience changes in their immune interactions." (PMID 40629041, 2025). "The multifaceted function of SMARCAL1 in tumor immunology is revealed by our pan-cancer research, indicating that it may be a useful target for cancer immunotherapy." (PMID 39994264, 2025). "Recent studies suggest that SMARCAL1 may play a role in tumor immune evasion, yet its pan-cancer role is unclear." (PMID 39994264, 2025). "As SMARCAL1 serves as a prognostic biomarker for cancer, we investigated whether there are any drugs specifically targeting SMARCAL1 in the CGP database." (PMID 39994264, 2025). "As a result, loss of RAD18 or UBC13 in BRCA1-deficient cancer cells does not abrogate reversed replication fork degradation, which is instead rescued upon knockdown of the fork reversal translocases SMARCAL1, ZRANB3 or HLTF." (PMID 38943334, 2024). "A key player in fork remodeling is a specialized DNA translocase known as SMARCAL1 (also designated HepA-related protein (HARP)) which is genetically linked to Schimke immune-osseous dysplasia, a disease with multiple defects involving the kidney, immune system, and cancer." (PMID 28594346, 2017).
cancer (continued). "Accordingly, depletion of these factors or SMARCAL1 sensitizes cancer cells to chemotherapeutics and can inhibit cancer cell growth, indicating that targeting these factors may be a powerful cancer therapy." (PMID 28117753, 2017). "By identifying SMARCAL1 as a dual regulator that simultaneously suppresses innate immune signaling and promotes immune checkpoint expression, this research suggests that targeting SMARCAL1 could provide a multifaceted approach to cancer treatment." (PMID 40629041, 2025). "The protein has emerged as a promising therapeutic target due to synthetic lethal interactions with BRCA1, SMARCAL1, and RAD52, and in ALT-positive cancers." (PMID 40447800, 2025). "According to recent studies, SMARCAL1 limits endogenous DNA damage and prevents signaling that is dependent on cGAS-STING during the growth of cancer cells." (PMID 39994264, 2025). "SMARCAL1 functions to limit endogenous DNA damage in cancer cells, thereby suppressing the activation of cGAS–STING-dependent signaling during cancer cell growth." (PMID 40629041, 2025). "It is, thus, possible that a similar synthetic lethality exists between SMARCAL1 and BRG1, that can be exploited for generation of small molecule inhibitors for cancer." (PMID 35784471, 2022). "Our results demonstrate the importance of intact SMARCAL1 helicase domains in suppressing characteristics of ALT in SMARCAL1 mutant, ALT-positive cancer cell lines." (PMID 29802247, 2018). "We conducted a comprehensive analysis of SMARCAL1 using TCGA, GTEx, and CCLE databases, evaluating its expression, genetic alterations, epigenetic modifications, and their clinical correlations across 33 cancer types." (PMID 39994264, 2025). "Initially, SMARCAL1‐mediated regulation of PD‐L1 in cancer patients could not be fully mimicked due to the study's heavy reliance on preclinical models, and the fact that SMARCAL1 does not affect the levels of PD‐L1 in mouse cells." (PMID 39247620, 2024).